CLEC14A (C-type lectin domain containing 14A)
Synonyms: EGFR-5; C14orf27; CEG1
Tractability: Antibody: UniProt predicts a signal peptide or a membrane-spanning region.
Gene: Protein-coding gene on chromosome 14 (38,254,000 to 38,256,093, reverse strand). Ensembl gene ENSG00000176435.
Subcellular location: Membrane
Subcellular location (Human Protein Atlas): Endoplasmic reticulum; Golgi apparatus
Gene Ontology:
Molecular function: extracellular matrix protein binding; protein binding; extracellular matrix binding
Biological process: cell migration involved in sprouting angiogenesis; vascular endothelial growth factor receptor-2 signaling pathway; vascular endothelial growth factor receptor-3 signaling pathway; cell migration
Cellular component: endoplasmic reticulum; external side of plasma membrane; extracellular matrix; membrane
Genetic constraint (gnomAD): Loss-of-function variants: 0 observed, 0.16 expected, observed/expected ratio (o/e) 0, 90% interval 0 to 1.88. That is too few expected variants to judge how well the gene tolerates losing a copy. Missense variants: 682 observed, 641.56 expected, observed/expected ratio (o/e) 1.06, 90% interval 1 to 1.13. Synonymous variants: 349 observed, 283.05 expected, observed/expected ratio (o/e) 1.23, 90% interval 1.13 to 1.35.
Homologues: Orthologues: chimpanzee CLEC14A (99% identical), macaque CLEC14A (94% identical), pig CLEC14A (78% identical), rabbit CLEC14A (72% identical), guinea pig CLEC14A (69% identical), mouse Clec14a (63% identical), rat Clec14a (63% identical), Caenorhabditis elegans ZK1193.2 (14% identical), Caenorhabditis elegans apx-1 (11% identical), Caenorhabditis elegans T25C12.3 (11% identical), Caenorhabditis elegans egas-1 (9% identical), Caenorhabditis elegans egas-4 (9% identical), and 3 more. Paralogues in human: CD93 (21% identical), CD248 (20% identical), DLL3 (12% identical), DLK2 (11% identical), CRELD1 (10% identical), CRELD2 (9% identical), WIF1 (8% identical), FBLN7 (8% identical).
Diseases named in the same sentence as CLEC14A in open-access papers:
CLEC14A is named in the same sentence as 36 diseases in open-access papers, as found by Europe PMC text mining. Sharing a sentence is not in itself a finding about the gene and the disease. The quoted sentences say what the papers report.
breast carcinoma (3 papers, 2008 to 2022). "Recently, C-type lectin domain family 14 member A (CLEC14A) has been identified as part of a molecular gene signature for tumor angiogenesis based on a meta-analysis on breast cancer, head and neck squamous cell carcinoma (HNSCC), and clear-cell renal cell carcinoma (ccRCC)." (PMID 35211124, 2022).
clear cell renal carcinoma (2 papers, 2022 to 2024). A malignant epithelial neoplasm of the kidney characterized by the presence of lipid-containing clear cells within a vascular network. "Clear cell renal carcinoma had the highest CLEC14a expression while normal liver and skin samples had higher CLEC14a expression than tumor samples." (PMID 38468017, 2024).
epithelial ovarian cancer (2 papers, 2017 to 2025). "CLEC14A has been implicated in tumor angiogenesis and endothelial cell adhesion, while CYYR1 is reportedly dysregulated in several malignancies including breast and ovarian cancers." (PMID 40601653, 2025).
hepatocellular carcinoma (2 papers, 2022 to 2026). A malignant tumor that arises from hepatocytes. "The authors found that the expression of CLEC14A was markedly increased in hepatocellular carcinoma tumors in comparison with the adjacent tissue, and the expression level of CLEC14A was positively correlated with the size and differentiation of the tumor." (PMID 35576868, 2022). "The current work aimed to investigate the expression and potential clinical significance of C-type Lectin domain family 14 (CLEC14A) in hepatocellular carcinoma." (PMID 35576868, 2022). "However, up to now, the potential roles of CLEC14A in hepatocellular carcinoma still need to be explored." (PMID 35576868, 2022). "Therefore, the authors designed the present study to investigate the potential clinical value of CLEC14A in hepatocellular carcinoma." (PMID 35576868, 2022). "The relative expressions of CLEC14A in the Hepatocellular Carcinoma (HCC) tissue and adjacent normal tissue of 105 HCC patients were examined using RT-qPCR methods." (PMID 35576868, 2022).
lung adenocarcinoma (2 papers, 2022 to 2024). A carcinoma that arises from the lung and is characterized by the presence of malignant glandular epithelial cells. "Some studies have found that CLEC14A methylation was associated with its expression and progression of lung adenocarcinoma and is a therapeutic target for solid tumors." (PMID 35634444, 2022).
lung carcinoma (2 papers, 2019 to 2023). "The stimulatory effects of BaP on angiogenic and tumorigenic genes including Clec14a, Efnb2, Id1, and Junb were higher in males than in females, which is consistent with the finding that the male sex is a significant risk factor for lung cancer in SLE patients, especially among smokers." (PMID 37047136, 2023).
renal cell carcinoma (2 papers, 2020 to 2021). "CLEC14A is expressed on the vasculature of tumours, more than half of renal cell carcinomas were high expression." (PMID 33761933, 2021). "In contrast, CLEC14A is expressed on the vasculature of a range of human solid tumours, with particularly high expression in more than half of renal cell carcinomas." (PMID 32696621, 2020).
Stroke (2 papers, 2020 to 2025). Sudden impairment of blood flow to a part of the brain due to occlusion or rupture of an artery to the brain. "For example, CLEC14A deficiency can exacerbate the neuronal loss post stroke by enhancing the pro-inflammatory response and blood-brain barrier permeability." (PMID 40264650, 2025). "Our previous study showed that CLEC14A KO mice developed abnormal vessels, so impaired angiogenesis due to CLEC14A deficiency might also have an effect on stroke." (PMID 32019570, 2020). "Pro-inflammatory cytokines, such as tumor necrosis factor alpha (TNF-α), interleukin 6 (IL-6), interleukin 1 beta (IL-1β), and monocyte chemoattractant protein-1 (MCP-1), were significantly increased in the CLEC14A-KO mice after stroke." (PMID 32019570, 2020). "Our results support that these pro-inflammatory mediators upregulated adhesion molecules and worsened the outcome of stroke in CLEC14A-KO mice." (PMID 32019570, 2020). "Further research is needed to understand the mechanisms of CLEC14A in angiogenesis after stroke and to determine if CLEC14A might be useful as a therapeutic target." (PMID 32019570, 2020).
alcoholic hepatitis (1 paper, 2020). Acute hepatitis resulting from ingestion of alcohol. "The meta‐analysis of the GEO dataset indicated that CLEC14A transcripts may be elevated in some non‐tumour pathologies, including alcoholic hepatitis, interstitial lung disease, lung idiopathic fibrosis and muscle from gastric cancer patients." (PMID 32696621, 2020).
breast tumor (1 paper, 2019). "To conclusively demonstrate a direct association between ACVRL1 and CLEC14A expression, we performed simultaneous RNAscope in situ hybridization on human breast tumor specimens." (PMID 30132150, 2019).
cerebral infarction (1 paper, 2020). An ischemic condition of the brain, producing a persistent focal neurological deficit in the area of distribution of the cerebral arteries. "CLEC14A KO mice had larger areas of cerebral infarction and severe neurological defects after ischemia-reperfusion injury." (PMID 32019570, 2020).
Cerebral ischemia (1 paper, 2020). Restriction of arterial blood supply to the brain associated with insufficient oxygenation to support the metabolic requirements of the tissue. "Next, we used a focal cerebral ischemia model (MCAO) with WT and CLEC14A KO mice to examine the loss of CLEC14A and high expression of VEGFR-2 during the pathological condition." (PMID 32019570, 2020).
cerebrovascular disorder (1 paper, 2020). A disorder resulting from inadequate blood flow in the vessels that supply the brain. "However, the functional significance of CLEC14A in cerebrovascular disorders remains unknown." (PMID 32019570, 2020).
chronic bronchitis (1 paper, 2020). A type of chronic obstructive pulmonary disease characterized by chronic inflammation in the bronchial tree that results in edema, mucus production, obstruction, and reduced airflow to and from the lung alveoli. "Studying non‐cancerous diseased human tissues, weak to moderate CLEC14A staining was detected on endothelial tissues in diseases of the lung such as chronic bronchitis, emphysema and chronic pneumonia, resembling that seen in healthy lung tissues." (PMID 32696621, 2020).
clear cell carcinoma (1 paper, 2020). "Studying protein expression in tumour tissues, we found that kidney tumours, and especially the most common type, clear cell carcinoma, expressed very high levels of CLEC14A protein." (PMID 32696621, 2020).
diseases of the liver (1 paper, 2020). "In diseases of the liver, including various forms of hepatitis, CLEC14A staining was generally weak or absent." (PMID 32696621, 2020).
Hepatitis (1 paper, 2020). Inflammation of the liver. "Equally, we were only able to test some liver and lung disease tissues for CLEC14A protein expression; although cases of hepatitis were generally negative, lower levels of CLEC14A protein were detected in some non‐cancer lung pathologies." (PMID 32696621, 2020).
ischemia (1 paper, 2022). A hypoperfusion of the BLOOD through an organ or tissue caused by a PATHOLOGIC CONSTRICTION or obstruction of its BLOOD VESSELS, or an absence of BLOOD CIRCULATION. "Another protein, the C-type lectin domain containing 14A (Clec14A), which interacts with VEGF and is involved in angiogenesis, has been associated with the loss of TJs during ischemia." (PMID 35755780, 2022).
ischemic stroke (1 paper, 2020). A stroke disorder caused by obstruction of blood flow to the brain, due to thrombotic (local blood clot formation) or embolic (due to a blood clot or other material traveling from another site) event. "Taken together, these results indicated that loss of CLEC14A induced a primary immune response by upregulated adhesion molecules and reactive glial cells during ischemic stroke conditions." (PMID 32019570, 2020). "Our results support the hypothesis that loss of CLEC14A increases cerebral vascular permeability because of the attenuation in junction-related proteins that occurs after ischemic stroke." (PMID 32019570, 2020). "Significantly more activated astrocytes were found in the CLEC14A KO mice after ischemic stroke, compared with the WT mice." (PMID 32019570, 2020). "In our study, the cerebral infarct was rescued by treatment with SU5416 in CLEC14A KO mice after ischemic stroke." (PMID 32019570, 2020). "The CLEC14A KO mice developed severe cerebral injury at 2 and 6 h after ischemic stroke and showed more EB dye leakage than WT mice." (PMID 32019570, 2020). "Therefore, our findings suggest that appropriate VEGF-A/VEGFR-2 signaling is important for the treatment of cerebral damage after ischemic stroke in the CLEC14A-KO mice." (PMID 32019570, 2020). "However, our results show that hyperactivated VEGFR-2 signaling in CLEC14A KO mice exacerbated BBB leakage and inflammatory response, with increased pro-inflammatory cytokines and glial activation induced by ischemic stroke." (PMID 32019570, 2020).
non-small cell lung carcinoma (1 paper, 2016). A group of at least three distinct histological types of lung cancer, including non-small cell squamous cell carcinoma, adenocarcinoma, and large cell carcinoma. "Increased expression of ROBO4, CLEC14A and ECSCR have also been associated with improvements in survival in non-small cell lung cancer." (PMID 26943033, 2016).
pancreatic cancer (1 paper, 2017). "CLEC14A and CD248 can bind MMRN2 simultaneously and this occurs at the interface between endothelium and pericytes in human pancreatic cancer." (PMID 28671670, 2017).
pancreatic ductal adenocarcinoma (1 paper, 2020). An infiltrating adenocarcinoma that arises from the epithelial cells of the pancreas. "A second pancreatic tumor model, murine pancreatic ductal adenocarcinoma (mPDAC), also expresses high levels of CLEC14A in the tumor vasculature." (PMID 33004686, 2020).
tumor (39 papers, 2013 to 2026). "Reduced tumor burden also correlated with significant loss of CLEC14A expression and reduced vascular density within malignant tissues." (PMID 33004686, 2020). "Moreover, much like CD93, CD248, TM, and CLEC14a, selectins and select galectins have been implicated in tumor angiogenesis and metastasis, the mechanisms of which expand the possibilities of study for the CTLDs at hand." (PMID 38468017, 2024). "Targeting of CLEC14A on tumour endothelium is potentially a new approach to regulating neutrophil infiltration in HCC." (PMID 42223241, 2026). "CLEC14A has been characterized as a tumor endothelial marker that plays a pivotal role in pathological angiogenesis." (PMID 40601653, 2025). "One group from the United Kingdom has demonstrated CLEC14a siRNA can be packaged into a chitosan nanoparticle and uptaken preferentially in tumor tissue of subcutaneously implanted LLC tumors in WT mice." (PMID 38468017, 2024). "CD93 and CLEC14A have overlapping binding sites in MMRN2, and appear to elicit similar responses in tumor vasculature upon deficiency." (PMID 38441970, 2024). "CLEC14A, a regulator of sprouting angiogenesis is considered a tumor endothelial marker, and its blocking has shown to decrease vascular density and the ability of sprouting angiogenesis." (PMID 36691028, 2023). "Since this protein family has been linked to tumor development (especially CD93, CLEC14A and CD248), there is a great interest in studying these proteins as possible therapeutic targets in cancer treatment." (PMID 37443812, 2023). "A single injection of CLEC14A-specific CAR-T cells was sufficient for a significant suppression of tumor growth in 3 distinct tumor models." (PMID 35211124, 2022). "The treatment of CLEC14A-redirected CAR-Ts significantly inhibited tumor growth in Lewis lung carcinoma, Rip-Tag2, and mPDAC mouse models without signs of toxicity." (PMID 36261831, 2022). "Increased expression of CLEC14A was correlated with tumor size (p = 0.0423) and differentiation (p = 0.0255)." (PMID 35576868, 2022). "CLEC14A is a tumour endothelial marker, it induces sprouting angiogenesis by directly binds to with MMRN2." (PMID 33761933, 2021). "In this study, we developed a novel angiogenesis score and feature genes (MMRN2, CLEC14A, ACVRL1, EFNB2, and TEK) which was associated with tumor angiogenesis microenvironment and prognosis in KIRC patients." (PMID 33761933, 2021). "It is here shown that an analysis of 5332 RNA expression profiles in the public domain confirmed high expression of CLEC14A in tumour compared to healthy human tissue." (PMID 32696621, 2020). "CLEC14A mediates filipodia formation and endothelial migration, plays a role in sprouting angiogenesis, and promotes tumor growth in mice." (PMID 33004686, 2020). "T cells expressing a chimeric antigen receptor specific for the tumor vascular marker CLEC14A inhibited tumor growth in three mouse cancer models." (PMID 33004686, 2020). "We did not detect CLEC14A protein in healthy liver tissues, and although we did detect some CLEC14A protein in lung tissue this was at a much lower level than that seen in some tumours." (PMID 32696621, 2020). "Earlier studies identified the transmembrane cell surface C‐type lectin CLEC14A as a putative tumour endothelial marker." (PMID 32696621, 2020). "Previous studies have demonstrated that CLEC14A is upregulated on vessels in this tumor and promotes tumor growth." (PMID 33004686, 2020). "We found that high CLEC14A/PECAM1 and CLEC14A/TIE1 ratios (ratio above 95% of controls) were significantly associated with tumour pathology (odds ratio = 2.5113, 95% CI: 1.7467–3.6104 and odds ratio = 8.9821; 95% CI: 6.7440–11.9630 respectively)." (PMID 32696621, 2020). "These CAR T‐cells specifically lyse CLEC14A‐expressing cells in vitro and reduce tumour growth in several mouse models (manuscript submitted)." (PMID 32696621, 2020).
tumor (continued). "High expression of CLEC14A on tumour blood vessels and its apparent role in tumour vascularisation make it an attractive target for tumour vasculature‐targeted immunotherapy." (PMID 32696621, 2020). "CLEC14A plays a role in angiogenesis, so targeting it should not only eliminate existing tumor vasculature, but it should also inhibit formation of new blood vessels in tumor tissue." (PMID 33004686, 2020). "In fact, the difference in the CLEC14A/TIE1 ratio alone was significant enough to allow the correct identification of sample status (healthy or tumour) in almost 75% of samples." (PMID 32696621, 2020). "Analysis of 112 normal tissues and 91 tumour samples indicated that CLEC14A expression accurately predicts tumour status (accuracy AUC = 83.7%; 95% CI: 0.779–0.885; p < 0.001) with sensitivity and specificity values above 75 and 85% respectively." (PMID 32696621, 2020). "ROC curve analysis of CLEC14A staining scores was performed in order to determine the sensitivity and specificity of CLEC14A expression levels in tumour tissues relative to healthy tissue samples." (PMID 32696621, 2020). "In the present study, we explored targeting tumor vasculature using CLEC14A-specific CAR-expressing T cells." (PMID 33004686, 2020). "For CLEC14A to progress as a vascular target in solid tumours an in‐depth analysis of CLEC14A expression in human healthy and tumour tissue is needed." (PMID 32696621, 2020). "Overall, CLEC14A mRNA expression per endothelial cell (expressed as CLEC14A/PECAM ratio) was significantly higher in the tumour group relative to healthy tissues." (PMID 32696621, 2020). "Poor tumour growth in CLEC14A (−/−) mice compared to wild type mice confirmed that CLEC14A promotes tumour growth." (PMID 32696621, 2020). "Although the CLEC14A-specific CARs inhibited tumor growth, some tumor tissue remained, supported by a reduced vasculature that largely did not express the target antigen." (PMID 33004686, 2020). "Expression of CLEC14A on tumour vasculature makes it a potential target for vascular disruption agents such as potent new cytotoxic immunotherapies." (PMID 32696621, 2020). "Similar to CD93, CLEC14A was described as a key gene in a proposed ‘tumour angiogenesis signature’ determined by meta‐analysis of over 1000 tumour samples including breast, renal and head and neck cancers." (PMID 31287944, 2019). "Among the 8 conserved genes across different tumor types, CLEC14A was the one with the highest mean co-expression coefficient." (PMID 30132150, 2019). "CLEC14A was initially described as a fundamental component of the cell-to-cell adhesion machinery and just a year later, a function as a tumor endothelial-specific marker was proposed." (PMID 30132150, 2019). "CLEC14A is considered as a candidate for tumor vascular targeting due to its presence at higher levels in tumor endothelium than in normal tissue endothelium." (PMID 31888692, 2019). "Thrombomodulin, CD93 and CLEC14A can be expressed by endothelial cells, whereas CD248 is expressed by vasculature associated pericytes, activated fibroblasts and tumour cells among other cell types." (PMID 31287944, 2019). "While CD93 and CLEC14A are expressed in tumor endothelial cells, endosialin is mainly expressed in pericytes." (PMID 29763414, 2018). "MMRN2 was previously found to be upregulated in tumor vessels in experimental cancer models, and to bind to CLEC14A." (PMID 29763414, 2018). "CD93 is a member of group XIV in the C-type lectin superfamily, which also includes thrombomodulin, CLEC14A, and endosialin, all of which are highly expressed in tumor vessels." (PMID 29763414, 2018). "The C-type lectin domain containing group 14 family members CLEC14A and CD93 are proteins expressed by endothelium and are implicated in tumour angiogenesis." (PMID 28671670, 2017).